IL17A (interleukin 17A)
Diseases named in the same sentence as IL17A in open-access papers (continued):
Sharing a sentence is not in itself a finding about the gene and the disease.
cognitive decline (24 papers, 2016 to 2026). "The authors suggested that it may be because chronic inflammation caused by Th17 cells and IL-17A leads to long-term cognitive decline in patients after IS." (PMID 37884768, 2024). "Higher baseline levels of IL-2, sCD40L, IL-8, and VEGF were associated with a lower annual cognitive decline in the aMCI group, and higher baseline levels of Aβ1–40, IFNγ, IL-5, IL-17A, IL-25, and FGF were associated with a rapid annual cognitive decline in the AD group." (PMID 34122046, 2021). "Patients with persistently elevated IL-17A levels show higher risks of cognitive decline, anxiety, and depression, as evidenced by lower scores on the Mini-Mental State Examination (MMSE)." (PMID 41357230, 2025). "Th17 cells and their effector cytokine, IL-17A, emerge as central players in this process, not only exacerbating ischemic injury but also contributing to long-term complications such as cognitive decline." (PMID 41357230, 2025). "Treatment with anti-IL-17A Abs inhibited the surgery-induced neuroinflammation and cognitive decline via alleviating the BBB disruption." (PMID 30501622, 2018). "We found that surgery induced cognitive decline, elevation of IL-17A and IL-17A receptor levels, production of pro-inflammatory cytokines and BBB dysfunction." (PMID 30501622, 2018). "Neutralizing IL-17A in an AD mouse model mitigated cognitive decline." (PMID 40469524, 2025). "These molecules, including interleukins (ILs) such as IL-1β, IL-4, IL-6, IL-9, and IL-17A, correlate with cognitive decline and disease progression, suggesting that a dysregulated inflammatory environment may affect cognition." (PMID 40507969, 2025). "We speculate that IL-17A increases neuroinflammation by changing the levels of inflammatory factors in the brain, thus exacerbating cognitive decline." (PMID 38098004, 2023). "In the aMCI group, higher baseline plasma levels of IL-2, sCD40L, and VEGF were associated with a lower cognitive decline, and in the AD group, higher baseline plasma levels of IFNγ, IL-5, IL-17A, IL-25, FGF, GM-CSF, and VEGF were associated with a more rapid cognitive decline." (PMID 34122046, 2021). "In contrast, the AD group showed that the higher baseline levels of IFNγ (r = −0.701, p = 0.036), IL-5 (r = −0.756, p = 0.019), IL-17A (r = −0.759, p = 0.021), IL-25 (r = −0.840, p = 0.036), and FGF (r = −0.780, p = 0.013) were significantly correlated with more rapid cognitive decline." (PMID 34122046, 2021).
juvenile idiopathic arthritis (24 papers, 2008 to 2025). Juvenile idiopathic arthritis (JIA) is the term used to describe a group of inflammatory articular disorders of unknown cause that begin before the age of 16 and last over 6 weeks. "DisGeNet analysis showed that especially IL-17A-induced changes in the transcriptome of chondrocytes and synovial fibroblasts are associated with juvenile arthritis, experimental arthritis, and musculoskeletal diseases, supporting that IL-17A could play an important role in OA." (PMID 34054865, 2021). "Furthermore, IL-17A+IFNγ+ cells can also arise when IL-17A+ cells are stimulated with IL-12 and upon exposure to synovial fluid from juvenile idiopathic arthritis (JIA) patients." (PMID 34082814, 2021).
Myocardial fibrosis (24 papers, 2012 to 2026). "In a rat model of aseptic pericarditis, IL-17A promotes the development of atrial fibrillation by inducing myocardial fibrosis." (PMID 39502194, 2024). "In a rat model of sunitinib-induced myocardial fibrosis, secukinumab (an IL-17A inhibitor) significantly attenuated myocardial fibrosis and improved left ventricular systolic and diastolic function." (PMID 39502194, 2024). "Interleukin-17 (IL-17) is a more specific pro-inflammatory cytokine that belongs to a new family of cytokines with no homology to other known interleukins, which are expressed in immune or non-immune cells, with IL-17A playing a key role in both myocardial inflammation and myocardial fibrosis." (PMID 40881586, 2025). "The area of myocardial fibrosis in noninfarctedheart was significantly smaller in IL-17A-KO (0.65±0.22%,n=11) and IL-23-KO (0.70±0.18%, n=9) mice than in WTmice (1.72±0.27%, n=10)." (PMID 23316306, 2012).
rosacea (24 papers, 2018 to 2026). A chronic erythematous skin disorder that affects the face. "Probiotics, such as certain strains of Lactobacillus, Bifidobacteria and Saccharomyces, can positively influence several immune mechanisms that are implicated in rosacea pathogenesis by increasing IL10 and reducing TNF-a, IL-17A." (PMID 40149947, 2025). "This aligns with evidence that IL-17A-neutralizing antibodies suppress CXCL5/CXCR2 axis activation in murine rosacea models, attenuating both inflammatory and fibrotic responses." (PMID 40474977, 2025). "The infiltration of CD4+ T cells and the expression of Stat1, Stat3, and IL-17A were repressed by EGCG treatment in rosacea-like mice." (PMID 36937834, 2023). "Moreover, TNF-α and IL-17A were also reported as the key cytokines in AD and rosacea." (PMID 34899707, 2021). "Altered adaptive immunity: Genes related to the Th1/Th17 pathway, specifically IL1B, IL6, IL17A, and IL22 are upregulated in rosacea patients compared to healthy skin controls." (PMID 39136023, 2024). "Adaptive T cell–derived cytokines IFNG, IL17A, IL17F, and IL22 were significantly overexpressed in lesional rosacea skin, while IL4 was either undetectable or not increased." (PMID 36633910, 2023).
scleroderma (24 papers, 2015 to 2025). Scleroderma is a rare autoimmune connective tissue disorder characterized by abnormal hardening of the skin and, sometimes, other organs. "Secondly, in an animal model, the secretion of IL-17A contributed to inflammation and the pathogenesis of scleroderma." (PMID 37445745, 2023). "A previous study showed that the secretion of IL-17A contributed to immune inflammation and the pathogenesis of scleroderma in an animal model." (PMID 33947424, 2021). "In vivo studies have shown that IL-17A-deficient mice were partially protected by bleomycin-induced scleroderma, and bleomycin-induced scleroderma was attenuated by anti-IL-17A antibody." (PMID 32823524, 2020). "In addition, a study by Wanget al. in a scleroderma model has also shown the ability of intraperitoneal metformin to dose dependently reduce IL-17A levels and RORγt expression and increase FOXP3 mRNA expression." (PMID 34386197, 2020). "Moreover, the presence of healthy human immune cells in scleroderma skin grafts may act as a sink for IL-6 protein and disrupt a positive feedback loop, such as been described for IL-6 and IL-17A." (PMID 37669366, 2023). "The immunofluorescence staining results showed that the proportion of IL-17A+/CD4+ cells was higher in hypertrophic scar and scleroderma tissues than in normal control tissues." (PMID 39872534, 2024). "We cultured CD4+ T cells with the supernatant of pyroptotic BMDMs in vitro, and the resulting T cells had a stronger ability to secrete IL-17A, indicating that GSDMD-related pyroptosis in macrophages could promote T cells differentiate into Th17, which may contribute to skin fibrosis in scleroderma." (PMID 35396386, 2022).
anemia (23 papers, 2018 to 2026). A reduction in the number of red blood cells, the amount of hemoglobin, and/or the volume of packed red blood cells. "Some other evidences have identified clinical biomarkers including anemia, first-line immunotherapy failure, and elevated CSF interleukin-17a (IL-17a) levels predictors of critical illness progression." (PMID 40170898, 2025). "In conclusion, free testosterone plays an essential role in pathogenesis in male mice by increasing CD8+ and decreasing Mac3+ cells and mainly reducing IL-17A levels, which is critical in the development of anaemia." (PMID 37384220, 2023). "Additionally, assessment of the systemic inflammatory markers demonstrated that IL6 and IL17A were progressively increased with duration of anemia demonstrating systemic inflammation in CA mice." (PMID 37234375, 2023). "Similarly, patients in the highest tertile of IL-17A had higher prevalence of anemia than those in the lower tertile." (PMID 35422004, 2022). "Results for IL-17A levels were also statistically significant when further adjusting for anemia, education, and LTBI (aOR, 1.96; 95% CI, 1.09-3.49) (eTable 1 in the Supplement) and in models using the mean of second-trimester and third-trimester values (n = 162) (aOR, 2.30; 95% CI, 1.18-4.49)." (PMID 34935918, 2021). "Similar results were observed in models further adjusting for anemia, educational level, and LTBI for IL-1β (aOR, 1.52; 95% CI, 1.15-2.01) and IL-17A (aOR, 2.36; 95% CI, 0.99-5.64) (eTable 1 in the Supplement)." (PMID 34935918, 2021). "These factors include anemia, a white blood cell (WBC) count in the cerebrospinal fluid (CSF) above 20 cells/mm3, failure to respond to first-line immunotherapy, and high-interleukin-17A (IL-17A) concentrations in the CSF." (PMID 38089115, 2023). "As we wondered whether IL-17A, IL-17F, IL-21, IL-17E, IL-22, and IL-23 levels could be abnormal in patients with AIG, we further measured these cytokines in the serum of AIG patients, iron deficiency anemia (IDA) patients without AIG, and healthy controls (HCs)." (PMID 35911678, 2022).
gingivitis (23 papers, 2012 to 2026). A disorder involving inflammation of the gums; may affect surrounding and supporting structures of the teeth. "The high TGF-β levels, accompanied by IL-6 in peripheral blood lymphocytes, activated Th17 cells and caused elevated percentage of CD4+ IL-17A+ Th17 cells in the peripheral blood of gingivitis patients, thereby secreting corresponding inflammatory factor IL-17A." (PMID 34234776, 2021). "The percentages of CD4+IL17A+Th17 cells and IL-17 significantly increased in the peripheral blood in the gingivitis group." (PMID 34234776, 2021). "Results of the present study revealed significant upregulation of TGF-β and IL-17A in gingivitis patients, relative to healthy controls." (PMID 34234776, 2021). "Analysis of CD4+IL-17A+Th17/CD4+CD25+Foxp3+Treg cells revealed a higher ratio in the gingivitis group, relative to healthy controls." (PMID 34234776, 2021). "Flow cytometry revealed significantly higher percentage of CD4+IL-17A+ T cells in the gingivitis group, relative to healthy controls." (PMID 34234776, 2021). "Moreover, the upregulation of IL-17A mRNA and RORγt mRNA were also found in the gingivitis group." (PMID 34234776, 2021). "ELISA results revealed higher levels of IL-17A, IL-10, IL-6 and TGF-β in plasma of gingivitis patients relative to normal controls." (PMID 34234776, 2021). "Results revealed significant upregulation of IL-17A and TGF-β in gingivitis patients, relative to healthy controls." (PMID 34234776, 2021). "Significantly, IL-17A+ Foxp3+ T cells are also found in human periodontal lesions but not in gingivitis." (PMID 32391008, 2020). "In this sense, a significant difference in IL-17A levels was also reported between PCOS subjects with or without gingivitis in serum, gingival crevicular fluid (GCF), and saliva." (PMID 32456146, 2020).
lymphoma (23 papers, 2011 to 2026). A malignant (clonal) proliferation of B- lymphocytes or T- lymphocytes which involves the lymph nodes, bone marrow and/or extranodal sites. "Five noninvasive biomarkers (FLT4, SFTPB, GNPTG, F5, and IL-17A) were further validated in an independent lymphoma cohort (n = 39), and another three noninvasive biomarkers (KIT, CCL3, and TNFSF1) were validated in NSCLC cohort (n = 76)." (PMID 38349411, 2024). "Interleukin-17A was first identified in activated rodent T lymphomas, termed CTLA-8, and subsequently identified in humans in 1995." (PMID 23956759, 2013). "To address this question, we validated eight plasma proteins (IL-17A, F5, FLT4, SFTPB, and GNPTG in lymphoma, TNFSF12, CCL3, and KIT in NSCLC) for response prediction and three plasma proteins (IL36G, SERPINC1, and LTA) for relapse monitoring." (PMID 38349411, 2024). "To identify specific predictive biomarkers, we selected five biomarkers (F5, FLT4, GNPTG, IL-17A, and SFTPB) that were differentially expressed between the R and NR patient groups in both lymphoma cohorts from the top 20% of significantly differentially expressed proteins (p < 0.05)." (PMID 38349411, 2024). "It is unclear whether the reduction in IFN-γ+ and increase in IL-17A+ T cells at 21 dpi relate to CD4+ T cell expansion and aggravation of lymphoma." (PMID 37631976, 2023).
pemphigus (23 papers, 2016 to 2025). Pemphigus is a group of rare autoimmune diseases that cause blistering of the skin and mucous membranes (mouth, nose, throat, eyes, and genitals).This conditioncan occur at any age, but often strikes people in middle or older age. "In line with previous human pemphigus studies, the data presented here confirm the overexpression of IL-17A, IL-17F, IL-17RA, IL-23A, and IL-23R in canine PF skin." (PMID 38393106, 2024). "Further studies will be needed to evaluate whether inhibitors of the IL-17 pathway (e.g., IL-17A, IL-17A/IL-17F, and IL-23A) could be used to treat the pemphigus group of blistering diseases in humans and dogs." (PMID 38393106, 2024). "Th17 cells are also present in lesional skin: accordingly, a comparison of the expression profiles of lesional versus perilesional and healthy skin from a patient with pemphigus identified an IL-17A-dominated immune signature, with high expression of genes involved in the IL-17A signalling pathway." (PMID 35187073, 2021).
Peri-Implantitis (23 papers, 2016 to 2025). An inflammatory process with loss of supporting bone in the tissues surrounding functioning DENTAL IMPLANTS. "The subgroup of studies focusing on cytokine polymorphisms (IL-1A, IL-1B, IL-10, IL-17A) demonstrated variable associations with peri-implantitis risk." (PMID 41373620, 2025). "In the Iranian population, the CC genotype of another IL-17A variant (rs10484879) was associated with CP and peri-implantitis." (PMID 26924897, 2016). "The current study supports the idea that the polymorphism of the IL-17A (-197 G/A) (rs2275913) genes may be a useful predictor for the pathogenesis of peri-implantitis." (PMID 38413570, 2024). "Additionally, these clinical indexes were also associated with cytokine levels in peri-implantitis in this study, which showed that IL-1β, IL-6, IL-17A, VEGF, CXCL2, and G-CSF had a positive correlation with these three clinical indexes." (PMID 36233685, 2022). "Similarly, in peri-implantitis, polymorphisms in cytokine- and matrix-related genes (such as IL-1β, IL-17A, and MMP-8) may exert comparable regulatory effects on gene expression, contributing to dysregulated inflammation and tissue destruction." (PMID 41373620, 2025). "Furthermore, the IL-17A GENE polymorphism (197 G/A) (rs2275913) is associated with peri-implantitis susceptibility and may serve as a predictive and prognostic biomarker." (PMID 38413570, 2024). "This is the first Iraqi dentistry study on the IL-17A SNP and peri-implantitis." (PMID 38413570, 2024). "Thus, the purpose of this study is to detect the role of the immune-genetic variation of IL-17A and related inflammatory cytokine (IL-23) in the initiation and progress of peri implantitis." (PMID 38413570, 2024). "Unfortunately, there were no studies concerning the IL-17A gene polymorphism in peri-implantitis to compare with the current study." (PMID 38413570, 2024). "Therefore, the aim of this study to detect the role of the immune-genetic variation of IL-17A and related inflammatory cytokine (IL-23) in the initiation and progress of peri implantitis." (PMID 38413570, 2024). "Furthermore, a classification model picked up biomarkers such as Peptostreptococcaceae XIG-1, Treponema, IL-6, and IL-17A to distinguish healthy implants from peri-implantitis." (PMID 36233685, 2022). "The genera of Peptostreptococcaceae XIG-1, Treponema, Porphyromonas, and Lachnospiraceae G-8, as well as the cytokines of IL-17A, IL-6, IL-15, G-CSF, RANTES, and IL-1β were significantly higher in peri-implantitis than healthy implants." (PMID 36233685, 2022). "In the same individual, peri-implantitis sites harbored more abundance of Treponema, Peptostreptococcaceae XIG-1, Porphyromonas, and Lachnospiraceae G-8, as well as cytokines of IL-6, IL-17A, G-CSF, RANTES, and IL-1β, than healthy implants sites." (PMID 36233685, 2022). "In this study, pro-inflammatory cytokines of IL-1β, IL-6, IL-17A, and TNF-α were significantly higher in peri-implantitis than those in healthy implants, and this result is consistent with another study." (PMID 36233685, 2022). "In conclusion, our study demonstrates that after three months of therapy, there was a significant reduction in the expression of cytokines in the peri-implant crevicular fluid of patients with peri-implant mucositis (IL-17A and TNF-α) and peri-implantitis (IL -1β, IL-6, and TNF-α)." (PMID 39860346, 2025).
skin cancer (23 papers, 2012 to 2025). "IL-17A is also associated with development of skin cancer via STAT3-mediating signaling in tumor and stromal cells, thus stimulating the penetration of myeloid cells into tumor environment." (PMID 30304852, 2018). "Our analyses showed a reduced presence of IL-17A-expressing TILs in cutaneous melanoma with respect to other skin tumors, such as squamous cell carcinoma or BCC." (PMID 34944746, 2021). "Furthermore, chronic UV-radiation exposure induces a local immune shift toward RORγt positive IL-17A/IL-22 producing ILC3 that are involved in mutant skin cell growth, thus promoting skin cancer." (PMID 35337918, 2022).
acute coronary syndrome (22 papers, 2012 to 2024). Signs and symptoms related to acute ischemia of the myocardium secondary to coronary artery disease. "Our previous clinical researches showed that Th17 cells and their characteristic cytokine IL-17A were associated with the plaque destabilization in patients with acute coronary syndrome (ACS)." (PMID 22808218, 2012). "Therefore, IL17A was considered by many investigators as pro-atherosclerotic and, as such, is associated with a possible acute coronary syndrome." (PMID 28352449, 2014). "Patients with acute coronary syndrome also have higher levels of IL-17A acutely during episodes." (PMID 38910708, 2024). "Moreover, as the concentration of this interleukin was shown to increase in patients with AMI, the enhanced IL17A concentration may partly justify the higher incidence of acute coronary syndromes in men." (PMID 28352449, 2014).